UGT1A2P (UDP glucuronosyltransferase family 1 member A2, pseudogene)
Synonyms: UGT1BP
Gene: Unprocessed pseudogene on chromosome 2 (233,747,214 to 233,748,079, forward strand). Ensembl gene ENSG00000228445.
Diseases named in the same sentence as UGT1A2P in open-access papers:
UGT1A2P is named in the same sentence as 1 disease in open-access papers, as found by Europe PMC text mining. Sharing a sentence is not in itself a finding about the gene and the disease.
UGT1A2P shares sentences with these, for which no sentence is quoted: neutropenia (1 paper).